CD4 (CD4 molecule)
Diseases named in the same sentence as CD4 in open-access papers (continued):
Sharing a sentence is not in itself a finding about the gene and the disease.
infection (continued). "The absence of CCR4 causes an imbalance in lung CD4+ and CD4+Foxp3+ cells, which exacerbates the Th1-mediated immune response, induces excessive pulmonary inflammation and progression of infection." (PMID 30584243, 2018). "A higher CD38 expression on CD4+ T cells from viremic HIV-1-infected people is a biomarker of poor prognosis and is strongly associated with short survival in patients with advanced infection." (PMID 30083165, 2018). "Recent evidence suggesting that macrophages may become positive for viral DNA through the capture and phagocytosis of infected CD4+ T cells implies a mechanism of infection distinct from virological synapse formation and furthers the debate." (PMID 29670623, 2018). "Our studies demonstrate that innate immune response particularly due to macrophage participation and adaptive immune response triggered by stimulation of CD4 cells play critical roles in elimination of parasitized erythrocytes during infection of mice with B. microti." (PMID 29445365, 2018). "Nevertheless, DC excel in their ability to capture HIV and facilitate infection of CD4+ T-cells." (PMID 29415518, 2018). "Finally, we reconstituted B6.Rag2−/− mice by adoptive transfer of CD4+ T cells prior to infection with L. donovani." (PMID 30619317, 2018). "T-dependent humoral immune responses to infection involve a collaboration between B and CD4 T cell activation, migration, and co-stimulation, thereby culminating in the formation of germinal centers (GCs) and eventual differentiation into memory cells and long-lived plasma cells (PCs)." (PMID 29568300, 2018). "Therefore M78 promoted SG colonization before acinar cell infection, by guarding infected, disseminating myeloid cells against CD4+ T cell engagement." (PMID 29447285, 2018). "However, the lifespan of CD4 Teff populations during specific infections has rarely been determined." (PMID 29630679, 2018). "Adoptive transfer of purified CD4+ T cells, but not B cells, prevented infection-associated weight loss and protected allanimals against a lethal infection with ZIKV MR766." (PMID 30087337, 2018). "This study adds novel information on other potential homing biomarkers such as CCR4, showing that in combination with CD27 (CD27−CCR4+IFN-γ+CD4+ T-cells) could be a phenotype to discriminate between disease and infection." (PMID 30687314, 2018). "Controlling for a range of factors, including viral load and infection length, the Swiss 4.5k Screen studying 4484 individuals found only a marginal independent impact of lower CD4+ T cell levels in individuals that mounted low levels of breadth and not those who had potent bnAb activity." (PMID 30055627, 2018). "Activated macrophages and proliferating CD4+ T lymphocytes are highly susceptible to infection, however resting CD4+ T cells and quiescent macrophages are largely non-permissive to HIV-1 replication." (PMID 29587790, 2018). "Next, we sought to determine whether all three infections could be given on the same day and yield a similar change in CD4 and CD8 TEM while condensing the experimental timeline." (PMID 29963060, 2018). "HIV disease progresses with time, and it would be expected, that individuals diagnosed with HIV at a higher age would also have advanced disease progression (lower CD4 cell count) because they, on average, had a longer time span between time of infection and time of diagnosis." (PMID 29378523, 2018). "Shortening the time from infection to measurement of CD4 cell counts could be an important window for early treatment." (PMID 29895275, 2018). "First, cohort CD4 count distributions suggest more advanced infection in the Canada/United States than in the Mexico cohort; we therefore cannot rule out a longer time for within-host escape mutations to accumulate (and, thus, enhanced ability to detect them) in the former." (PMID 29093100, 2018).
infection (continued). "Virus-dependent decreases in peripheral blood CD4 + T cell counts were small but statistically significant at 6 months post-infection, prior to cART initiation (544 ± 129 × 103/μL compared to 768 ± 122 × 103/μL pre-infection, p = 0.034), and normalized after cART treatment." (PMID 30361514, 2018). "We analyzed JunB expression in splenic CD4+ T cells from naïve and P. yoelii 17XNL-infected mice, as shown in S6 Fig, P. yoelii 17XNL infection induced a significant increase in JunB expression in splenic CD4+ T cells, but the levels were not significantly different between the two groups." (PMID 30462731, 2018). "We depleted CD4+T cells from Ifnar1-/- mice prior to infection with ZIKV." (PMID 30212537, 2018). "Higher numbers of IL-10 producing CD4+ cells together with increased Treg cell numbers supports participation of these immune responses in suppression of excessive inflammation during simultaneous infection by B. burgdorferi and B. microti in C3H mice." (PMID 30619263, 2018). "Thus it is possible that in natural hosts, the lower ratio of TCM infection is related to the control of viral replication in LN, whereas the predominant virus replication in the gut would explain why most virus infects CD4+ effector T cells in natural hosts." (PMID 29725327, 2018). "Importantly, there were significantly fewer E641-bound CD4+ T cells post-infection in the brain of old mice compared to the adults even though the number of E641-bound CD4+ T cells present in the spleen of these mice when comparable on day 10 (not shown)." (PMID 29864157, 2018). "A switched antigen-specific CD4+T response from a systemic Th1 to a Th17 dominated mucosa-resident response as well as local IgA response correlate with increased protection against mucosal pathogen infection." (PMID 30619341, 2018). "Importantly, the formation of TNT by DC favors trans-infection of targeted CD4+ T lymphocytes at a relatively long distance, similar to what happens between two distant CD4+ T lymphocytes." (PMID 29422895, 2018). "Indeed NK1.1+CD4+ T cells more frequently expressed the early apoptosis indicator Annexin V from day 5 to day 14 after infection relative to NK1.1−CD4+ T cells." (PMID 30374346, 2018). "Notably, studies have shown that CD4+ T cells play a primary role in the early infection of A. cantonensis." (PMID 29843794, 2018). "Seven days after infection, the CD4+T cell-depleted Ifnar1-/- mice showed a significant difference in weight that was maintained until day eleven post infection, when the CD4 depleted mice began to succumb to infection." (PMID 30212537, 2018). "Infection decreased circulating CD3+CD4+ T-cells throughout the course of the experiment." (PMID 30072754, 2018). "Moreover, anti-HSV CD8 T cell responses in MHC II knockout and/or CD4 T cell antibody depleted mice were impaired at peak primary (day 7 post infection) and memory (90–110 days post priming) time points." (PMID 29872429, 2018). "Whether the epitope specific CD4+T cell response utilizes a broad or narrow set of TCRs does have implications for the outcomes to infections." (PMID 30212537, 2018). "Next, in order to investigate whether GcfAB elicits CD4 T-cell responses upon RSV B subtype infection, GcfAB-immune mice were challenged with an RSV B (KR/B/10-12) clinical isolate with the same 131–230 amino acid sequence as GcfB." (PMID 28384263, 2017). "Thus, HIV‐1 entry into DCs triggers a signaling response that regulates trans‐infection of the virus to CD4+ T cells, promoting disease transmission." (PMID 28923824, 2017). "Overall, these data suggest that attenuation of swelling during Opal524R infection may be due in part to a failure to recruit high levels of CD4+ T cells and NK cells but cannot be explained by differences in monocyte recruitment." (PMID 29138302, 2017). "Interestingly, after infection (43 dpi), a high proportion of antigen specific CD4+ T cells expressing CD44 and CD69 were observed in both NGP5B and NGP5B+CPG mice." (PMID 29069089, 2017).
infection (continued). "In addition, localization of CD4 T cells in close proximity to infected DCs is likely to be an important determinant of the type of antigen-specific CD4 T cells mobilized after infection." (PMID 28767735, 2017). "Therefore, we believe that a minor number of CD4-induced open Env trimers (∼10%) as determined by EM analysis are still sufficient to mediate productive infection of TZM-bl cells that express high levels of CD4 and CCR5 on their surface." (PMID 28743743, 2017). "To determine why the rate of expansion differed between memory and naïve-derived CD4+ T cells, we compared the timing of T cell activation and differentiation, and the ability of memory vs. naive T cells to expand on a per-cell basis during infection." (PMID 29176787, 2017). "All CD4+IFNγ-/- T cell recipients that finally succumbed to the infection continuously lost weight and developed a clinical score with similar kinetics or even a little earlier than control mice, whether treated with isotype or anti-TNFα antibody." (PMID 28222146, 2017). "Initial data in this regard came from Southern Europe from intravenous drug abusers who share syringes, leading to a decrease in the number of T CD4 lymphocytes; in 90% of these patients, the infection represents reactivation of a previously acquired subclinical or latent infection." (PMID 28649370, 2017). "To determine whether this activated phenotype is correlated with a higher functional activity, we isolated CD4+ Foxp3+ Tregs from mLN at day 10 post infection and cultured them with CD4+ responder T cells." (PMID 28938014, 2017). "We hypothesized that BM CD4+ T cells might drive the alterations observed in the hematopoietic compartment during infection." (PMID 28671989, 2017). "Nevertheless, more CD4+ T cells were found 6 h after infection." (PMID 28883509, 2017). "This suggested that eSF might induce phenotypic changes in CD4+ T cells to render them more permissive to infection." (PMID 28207890, 2017). "In contrast, previous studies have successfully selected the viruses that acquired the ability to counteract stable A3H in the in vitro culture infection experiments using the human CD4+ T cell lines such as MT-4 cells and SupT11 cells that ectopically express A3H-II." (PMID 28475648, 2017). "Given the comparable levels of elicited antibodies, and the potential for vaccine-elicited CD4+ T cells both to protect from infection and to serve as targets for infection, MVAgp140 and the more generally used gp120 boost immunogens merit further evaluation for advancement to clinical studies." (PMID 29021394, 2017). "Interestingly, CD169-mediated capture of HIV-1 in macrophages leads to virion retention in the VCC and subsequent transfer to and productive infection of CD4+ T cells." (PMID 29250073, 2017). "However, for a hepatitis C virus (HCV) vaccine to be effective in preventing infection, it must be capable of generating cross-reactive CD4+, CD8+ T cell, and NAb responses that will cover the major viral genotypes." (PMID 29163442, 2017). "However the greater effect of CD4+ T cell depletion than IFNγ neutralization on lung myeloid cell infection implied that target cell recognition was the key parameter, rather than susceptibility to IFNγ." (PMID 28394921, 2017). "In L. donovani infected mice, CD4+ Th1 responses typically peak between day 21 and 28 of infection." (PMID 28892492, 2017). "This may require altered coreceptor usage, or modifications to allow infection of cells that express lower CD4 levels." (PMID 28264054, 2017). "Importantly, a recent study showed that NK cells can suppress CD4+ T cells and Tfh cells in a perforin-dependent manner during the first few days of infection, resulting in a weaker germinal center (GC) response and diminished immune memory." (PMID 28488245, 2017). "The CD4 model estimated an annual decrease of 4.6% in new infections from 2008 to 2013." (PMID 28159730, 2017).
infection (continued). "We measured the levels of neutrophils, B cells, and CD4+ T cells in colonic tissue samples at four time points, as well as the level of bacterial shedding in the stool at 14 time points, spanning the course of infection." (PMID 27821583, 2017). "Neither baseline CD4 cell count nor recency of infection defined by RITA was associated with risk of TDRMs." (PMID 27476929, 2017). "To determine whether eSF-mediated enhancement occurs in the presence of semen fibrils, we combined the two components, and found that eSF and semen fibrils synergistically enhanced BaLGFP infection of CD4+ T cells." (PMID 28207890, 2017). "A humanized mouse model of HIV infection demonstrated that T cells expressing optimized CARs were superior at expanding in response to antigen, protecting CD4 T cells from infection, and reducing viral loads compared to T cells expressing the original, clinical trial CAR." (PMID 29023549, 2017). "Preferential Gag-specific CD8+ T cell responses have also been observed in viremic controllers and limited infection of CD4+ central memory cells, perhaps related to low CCR5 expression on these cells, seem to be associated with lack of disease progression in VNPs." (PMID 28331526, 2017). "Furthermore, CD4+IFNγ-/- T cells provided long-term control in those animals that survived the infection." (PMID 28222146, 2017). "The infection level in resting memory CD4+ T cells, involving HIV entry and integration, might determine the size of the viral reservoir." (PMID 29085362, 2017). "At the same time, induction of immune activation in natural SIV infection in AGMs can lead to partial CD4 loss in an otherwise non-pathogenic infection." (PMID 28829402, 2017). "infection is particularly frequent in AIDS patients with CD4+ T cell counts of <100 cells/μL." (PMID 29295550, 2017). "In order to further distinguish whether CD4+ T lymphocytes were the immune cells involved in the anti-infection effect by bivalent flagellin vaccine in vivo, CD4+ or CD8+ T lymphocytes were depleted independently by corresponding antibodies." (PMID 29201922, 2017). "Finally, we demonstrate that, in contrast to IL-4 DCs, IFN-α DCs are impaired in their capacity to transfer HTLV-1 to CD4 T-cells, both after viral capture and trans-infection and after their productive infection." (PMID 28426803, 2017). "Cryptococcal IRIS is thought to be the result of patients developing a new C. neoformans infection (relapsing) or the reactivation of a latent or sub-clinical infection following anti-viral therapy, which in turn activates pathologic CD4+ T-cell mediated immune responses to fungal antigens." (PMID 29371497, 2017). "Furthermore, a proportion of NKG2C+NKG2A− NK cells >35.45%, and a ratio of NKG2C/NKG2A >1.7 were predictive for higher CD4+ T cell counts 720 days after infection." (PMID 28979268, 2017). "Higher proportions of neutrophils and elevated CD4+/CD8+ T cell ratios during the first days after challenge were correlated with early production of gamma interferon (IFN-γ) and associated with controlled infection." (PMID 27799331, 2017). "In addition to engaging Env, these sulfopeptides prevent CD4-Ig from enhancing infection at low concentrations or when cellular CD4 was limiting." (PMID 28422793, 2017). "In agreement with previous studies, we speculate that the residual CD4 T cells may have helped to eradicate the infection in these animals by producing neutralizing antibodies to block the viral spread." (PMID 29208932, 2017). "This phenomenon indicated that CD4+IL-17+Th17 cell-mediated immune response might be responsible for the anti-infection activity afforded by the bivalent flagellin when antiopsonophagocytic killing and antimotility antibody levels were low." (PMID 29201922, 2017). "Although the guidelines from the Center for Disease Control and Prevention (CDC) emphasize that HIV-infected patients with a CD4 T-cell count lower than 50 cells/μl are more susceptible to infection with NTM but not with TB." (PMID 29092717, 2017).
infection (continued). "This indicates that loss of CD27 expression on M. tuberculosis–specific CD4+ T cells, while associated with clinical disease, is not related to time since infection in patients with LTBI." (PMID 28329119, 2017). "Infections with L. amazonensis differ from other Leishmania species infections due to their ability to suppress the activation and functions of immune cells, like macrophages, dendritic cells, and CD4+ T cells." (PMID 28848541, 2017). "In response to infection, T-bet and Egr2 were induced in CD4 and CD8 T cells." (PMID 28455436, 2017). "The rate of CD4 T-cell loss and the subsequent course of infection are determined by the “set point” of CD8 T-cell activation established within the first 6 months following infection." (PMID 28993778, 2017). "The authors concluded that the killing of liver cells may also implicate CD4 CTL in the manifestation of liver disease that is frequently observed upon secondary infection." (PMID 28167943, 2017). "CD4+ T cells can be divided into two subsets, Th1 and Th2, the imbalance of which can lead to decreased immune function, thereby weakening the body's ability to resist infection." (PMID 28225889, 2017). "We showed in vitro that if the CAR+ CD8 T cells are in sufficient numbers, they can prevent the spread of infection in all cells; however, if they fall below a critical level, then both the CD4 T cells as well as the CAR+ CD8 T cells are infected and HIV begins to spread." (PMID 29023549, 2017). "Thus, the size of the MCMV inoculum predominantly affects the formation of EM-like CD8+ T cells throughout the course of infection while aging seems to predominantly impact the percentages of EM-like CD4+ T cells." (PMID 29367854, 2017). "Using the β-lactamase reporter system, we could demonstrate that upon infection via the natural route Yersiniae can directly modulate CD4+ T cells within infected mLNs, extending previous findings from a systemic infection model." (PMID 28378044, 2017). "Interestingly, the results obtained in this study also highlighted that the CD4+/CD8+ ratio was higher in controlled-infection than in persistent-infection granuloma-like structures." (PMID 27799331, 2017). "Similarly, CD4+ cytotoxic T lymphocytes (CD4+ CTL) have been described for their direct contribution to control infections and malignancies as being capable of lysing class II-expressing targets." (PMID 28289418, 2017). "In utero MTCT may depend upon initial infection of placental macrophages (e.g., Hofbauer cells), which have low surface densities of CD4 molecules." (PMID 28122636, 2017). "Increased K. pneumoniae lung burden was also associated with a significant decrease in the number (expressed as the absolute number of T-cells post infection minus the absolute number of T-cells prior to infection) of CD4+ and CD8+ T-cells in the lungs of alcohol-fed mice (respectively)." (PMID 28604843, 2017). "Since DC-specific IL-10 ablation in P. yoelii-infected mice interfered with the induction of IL-10-producing CD4+ Tr1 cells and resulted in elevated production of pro-inflammatory cytokines, we monitored progression of blood infection by microscopic examination of Giemsa-stained blood films." (PMID 28293237, 2017). "Similarly, at day 14 post-infection, numbers of CD4+, CD8+ or TCRβ– NK1.1+ (NK) cells producing IFN-γ in the perigonadal fat or lung remained unaltered." (PMID 29040326, 2017). "Our findings reveal common and distinct signaling pathways altered by HIV-1 depending on the presence of microbes that may shed light on infection, inflammation and CD4+ T cell depletion in HIV-1 infected individuals." (PMID 28241075, 2017). "From studies of human HIV infection and of SIV infection of non-human primates it has been recognized that sterile protection must be achieved to prevent seeding into reservoirs such as latently infected CD4+ T cells or immunologically privileged sites, which happens rapidly after infection." (PMID 28166802, 2017).